IL1B (interleukin 1 beta)
Diseases named in the same sentence as IL1B in open-access papers (continued):
Sharing a sentence is not in itself a finding about the gene and the disease.
ulcer (continued). "The very specific localization of IL-1β in the areas of epithelial cell damage in ulcers suggests that disruption of the epithelial barrier may be a primary event." (PMID 34675383, 2021). "In addition, ulcers in diabetic patients show a complete derangement of inflammation mediators: interleukin (IL)-1β, IL-6, tumor necrosis factor-α (TNF-α)." (PMID 33227909, 2020). "Moreover, it has been suggested that cell killing activates inflammasome and IL-1β production and this inflammatory response leads to tissue damage and ulcer development." (PMID 32851099, 2020). "Pretreatment of ethanol-injected rats with both omeprazole and manuka honey caused a significant decrease in plasma TNF-α (38% and 28%) (P = 0.000 and 0.000), IL-1β (49% and 50%) (P = 0.000 and 0.000), and IL-6 (45% and 47%) (P = 0.000 and 0.000) as compared to the ulcer-induced rats." (PMID 26770649, 2016). "They found that sufficient inhibition of gastric acid by omeprazole inhibited both ulcer recurrence and responses, which suggested that acid may enhance gastric mucosal inflammation in response to IL1-β stimulation, resulting in gastric ulcers." (PMID 26465592, 2015). "MSE was reported to reverse the increase of TNF-α and IL-1β in GU induced by AA in normal rats and promoted ulcer healing by its various effects on gastric mucosal defensive factors including enhanced cell proliferation and antioxidants and reducing free radicals levels." (PMID 24192345, 2013). "In addition, IL-1β is considered as a major factor responsible for the induction of ulcer recurrence." (PMID 21423634, 2011). "In addition, IL-1β significantly increased intercellular adhesion molecule 1 expression and leucocyte infiltration in the scarred mucosa’s superficial region before ulcer recurrence." (PMID 36712695, 2022). "However, IL-8 paired with IL-1β measurements in saliva, could improve the validity of pre-empting an active ulcer episode." (PMID 35003055, 2021). "A direct comparison between the ulcer + OMP and ulcer + OMP-NS groups revealed that the OMP-NS formulation significantly decreased levels of HMGB1, NLRP3, NF-κB, TLR-2, MyD88, IL-1β, IL-6, and TNF-α." (PMID 40563542, 2025). "mRNA levels of IL-1β, IL-6, IL-18, and TNF-α in the ulcer tissue were significantly reduced following butyrate treatment, while the levels of tight junction proteins Claudin-1 and ZO-1 were significantly elevated." (PMID 40818135, 2025). "In CL, ulcer development results from the combined presence of Th1 cytokines (such as IFN-γ and TNF), IL-1β, and cytotoxic activity from CD8 + T cells." (PMID 40982482, 2025). "In uninfected ulcer patients, NLRP3 expression correlated with IL-1β, whereas in infected groups, active caspase-1 was closely associated with both GSDMD-N and mature IL-18, supporting canonical pyroptosis activation." (PMID 40563885, 2025). "In uninfected ulcer patients, a significant correlation was seen between NLRP3 expression and IL-1β expression." (PMID 40563885, 2025). "Therefore, reducing levels of TNF-α, IL-1β, and IL-6 may promote ulcer healing." (PMID 38398633, 2024). "Similar to omeprazole, NPW treatment significantly reduced gastric and serum tumor necrosis factor-alpha and interleukin-1 beta levels and depressed the upregulation of nuclear factor kappa B (NF-κB) and COX-2 expressions due to ulcer." (PMID 38227096, 2024). "Meanwhile, AR can prevent the damage of gastric mucosa induced by indomethacin and promote ulcer healing through reducing TNF-α, IL-1β, and MPO, and increasing the PGE2 in the gastric tissue." (PMID 37109624, 2023). "In another study, administration of G. biloba ameliorated gastric lesions, with a significant decrease in ulcer score, MPO, and IL-1β and a significant rise in GSH, mucus content, and gastric pH." (PMID 36080365, 2022). "We analyzed the ulcer area, conducted histological analysis, and measured the levels of the inflammatory cytokines TNF-α, IL-6, IL-1β, and IFN-γ, and anti-inflammatory cytokine IL-10 by ELISA." (PMID 35456589, 2022).
ulcer (continued). "More so than in the pre-treated animals, the EGb 761-treated groups showed improved score, levels, and expressions of the ulcer index, MDA, GSH, NO, IL-6, TNF-α, IL-1β, COX-2, and PCNA." (PMID 36080365, 2022). "In contrast with control cohort, the amounts of IL-1β, IL-6, TNF-α, IL-18 in ulcer model cohort increased to 8.52-, 5.24-, 7.86-, and 4.16-folds, respectively." (PMID 34975497, 2021). "Treatment with NADA and AM630 protected gastric tissues against ulcers as demonstrated by a decrease in the contents of MDA, TNF-α, MPO, and IL-1β along with an increase in the content of PON-1 activity and GSH in the stomach tissues." (PMID 35083004, 2021). "Activation of nuclear factor-kappaB (NF-κB) is a vibrant pathophysiological process during ulcer formation, which stimulates pro-inflammatory cytokines, such as TNF-α and IL-1β." (PMID 28587230, 2017). "All these events initiate an inflammatory phase of ulcer development with recruitment and metabolic activation of neutrophils and macrophages, releasing pro-inflammatory cytokines (TNF-α and IL-1β) and generating free radicals." (PMID 24416280, 2014). "Sesamol significantly decreased gastric ulceration and hemorrhage and inhibited mucosal TNF-α, IL-1β, and IL-6 production and NF-κB activity in WIR-treated rats." (PMID 23984371, 2013). "Recently, we reported the healing effects of ethanolic extract of dried fruit pulp of MS (MSE) on acetic acid induced gastric ulcer in normal (NR) rat and found the role of cytokines, TNF-α, IL-1β and growth factor, TGF-α in healing ulcer." (PMID 24192345, 2013). "Ulcer index was calculated based upon the product of length and width (mm2/rat) of ulcers while, TNF-α, IL-1β and TGF-α were estimated in the gastric mucosal homogenate from the intact/ulcer region." (PMID 24192345, 2013). "Of the 24 subjects with active ulcers, TNF-α was detectable in 18 and IL-1β was detectable in 14 participants." (PMID 23922670, 2013). "Morerecently, a study investigating functional gene polymorphisms in people with RAS showed a marked increase in the IL-1β and TNF heterozygousgenotypes in ulcer sufferers." (PMID 19259334, 2008). "Considering the broad role of inflammatory cytokines in the regulation of the WH process, we evaluated the expression of COX2 and pro-inflammatory cytokines, namely IL1β, IL6, TGFβ, and TNFα, that are important for cell proliferation and the synthesis of the ECM, both in normal-HDFs and ulcer-HDFs." (PMID 38671778, 2024). "In the gastric tissue and serum samples of saline-treated ulcer group, levels of the pro-inflammatory cytokines TNF-α and IL-1β were both elevated as compared to control group (p < 0.001), while the anti-inflammatory IL-10 level was depressed (p < 0.001–0.001)." (PMID 38227096, 2024). "In this study, we proposed that the ability of Cls to block ROS, IL-1β, IL-6, TNF-α, NF-κB, and caspase-3 as well as increase pErk-1, NO, PECAM-1, and PPAR-γ levels partly explains why it protects the stomach against ethanol-induced ulcer." (PMID 38884677, 2024). "Furthermore, studies have shown a pathogenic role of CD8+ T cells at the lesion site, as the lyses of infected cells release molecules that induce the secretion of IL-1β, TNF, inflammasome activation, and the appearance of the ulcer." (PMID 32851099, 2020). "In particular, the high level of IL-1β correlates with non-healing ulcers, severe wound healing disturbances, and scar formation." (PMID 33489037, 2020). "Plasma concentrations of the proinflammatory cytokine IL1-β (pg/mL) (ssu vs. ssn median(IQR): 0.34 (1.28) vs. 0 (0.08); p = 0.0178), but not TNF-α (pg/mL) (1.99 (4.3) vs. 0.97 (3.38) was significantly greater in subjects with ulcers." (PMID 23922670, 2013). "Additionally, immunohistochemical staining revealed that IL-1β is localized to the ulcer bed and granulation tissue (top), but not to noninflamed tissue or that where lymphoid aggregates predominate (top)." (PMID 34675383, 2021).
ulcer (continued). "Interestingly, in this study both BD-MQ and RAS-MQ (RAS data not included) had higher levels of salivary IL-8 and IL-1β to that of HCs, suggesting their continued presence during non-ulcer periods may reflect the mucosal instability of these patient groups." (PMID 35003055, 2021). "In agreement with the literature, a more intense expression of COX2, IL1β, IL6, TGFβ, and TNFα was observed in ulcer-HDFs than in normal-HDFs." (PMID 38671778, 2024). "The frequency of cytokine detection in sickle cell disease patients without ulcers was lower in comparison to the ulcer group, which showed 12 of 31 presenting with detectable concentrations of TNF-α and 10 with IL-1β." (PMID 23922670, 2013).
cardiac hypertrophy (71 papers, 2007 to 2025). "Previous studies have shown that proinflammatory cytokines, such as TNF-α, IL-1β, and IL-6, are closely associated with myocardial fibrosis, pathological cardiac remodeling, and myocardial hypertrophy." (PMID 38158445, 2023). "In support of having a detrimental role during cardiac hypertrophy, IL-1β deficient mice undergoing pressure overload exhibited improved cardiac function and reduced cardiac hypertrophy, indicating that IL-1β promotes pathological hypertrophy." (PMID 33324685, 2020). "KO also promoted D-gal-induced cardiac hypertrophy and increased myocardial IL-1β and IL-6 levels, as well as the number of β-gal-positive cells." (PMID 39511427, 2024). "Studies employing pharmacologic blockade or ribonucleic acid (RNA) interference targeting NLRP3, as well as the inhibition of IL-1β with neutralizing antibodies, have demonstrated mitigated pressure overload-induced myocardial hypertrophy." (PMID 38791409, 2024). "In vivo andex vivo models of cardiac hypertrophy have demonstrated a significantupregulation in caspase-1 and IL-1β expression." (PMID 39484135, 2024). "By 6 months of age, SHRs continue to haveelevated blood pressure and exhibit increased myocardial hypertrophy, fibrosis,and inflammation, along with elevated levels of IL-6, IL-1β,TNF-α, and TGF-β1." (PMID 39076555, 2024). "A cardiac-specific miR-30a-5p sponge also promoted D-gal-induced cardiac hypertrophy and myocardial IL-1β and IL-6 levels, along with an increase in β-gal-positive cells." (PMID 39511427, 2024). "This complex activation subsequently triggers NLRP3 inflammasome activation and IL-1β production, fostering myocardial hypertrophy." (PMID 38791409, 2024). "In Ang II-induced hypertension rats, a blockade of TLR4 delayed the progression of hypertension and reduced the TNF-α and IL-1β levels and NF-κB activity in myocardial tissue, which improved cardiac hypertrophy." (PMID 36247184, 2022). "Cardiac hypertrophy can occur in response to proinflammatory cytokines, such as IL-6 and IL-1β, and can be required for maintenance of cardiac homeostasis." (PMID 34669512, 2022). "Pharmacologic blockade or RNA interference of NLRP3 and inhibition of IL-1β can reduce pressure overload-induced myocardial hypertrophy." (PMID 35509275, 2022). "The NLRP3 inflammasome is activated and increases caspase-1 and IL-1β expression in a rat myocardial hypertrophy model developed by aortic transverse contraction and in human cardiomyocytes treated with angiotensin II." (PMID 36111168, 2022). "Pyrroloquinoline quinone inhibited ROS and NF-κB activation inhibited NLRP3 inflammasome and Caspase-1, IL-1β and IL-18 expression, and improved myocardial hypertrophy and cardiac fibrosis." (PMID 35509275, 2022). "The high expression of IL-1β is observed in patients with cardiac form of Chagas disease, and its action is correlated to cardiac hypertrophy and inhibition of fibroblast proliferation, indicating the IL-1β role in cardiac remodeling." (PMID 34336720, 2021). "Many pro-inflammatory factors are involved in pressure overload-induced cardiac hypertrophy in mice, including IL-1β, IL-6, IL-18, and TNF-α." (PMID 34168567, 2021). "Pharmacologic blockade or RNA interference of NLRP3 and inhibition of IL-1β with neutralizing antibody reduced pressure overload-induced myocardial hypertrophy." (PMID 34776995, 2021). "Collectively, this study revealed a previously unrecognized involvement of caspase-1 in cardiac HP by regulation of IL-1β and IL-18 and shed light on caspase-1 as an antecedent indicator and target for cardiac hypertrophy." (PMID 33842546, 2021). "Cardiac hypertrophy significantly increased the percentage of apoptotic cells and upregulated IL-1β, cleaved caspase-1, and GSDMD-N that lie downstream of the NLRP3 inflammasome." (PMID 33723236, 2021). "In the present study, we have observed enhanced expression of inflammatory genes such as TNF-α, IL-6, and IL-1β in hypertrophy heart." (PMID 32082481, 2020).
cardiac hypertrophy (continued). "In contrast, phytopharmaceuticals, such as asiatic acid, not only repressed IL-1β-induced cardiomyocyte hypertrophic response, but also suppressed upregulation of IL-1β as well as TAC-induced cardiac hypertrophy." (PMID 33324685, 2020). "Cardiac-specific overexpression of human interleukin 1α (IL-1α) results in cardiac hypertrophy, and systemic administration of IL-1β antibodies or IL-1β deletion prevents aortic banding-induced hypertensive cardiac hypertrophy." (PMID 32831633, 2020). "The results showed that LCZ696 significantly improved heart dysfunction, cardiac hypertrophy, and fibrosis and inhibited the expression of proinflammatory factors IL-6, IL-1β, and TNF-α in the circulating blood and heart tissues of mice." (PMID 32420365, 2020). "Another study further showed that activation of caspase-1-dependent pyroptosis plays a role in the pathogenesis of cardiac hypertrophy, especially its activation upregulated IL-1β expression and promoted IL-1β transformation to the active state." (PMID 33324685, 2020). "For example, some inflammatory cytokines such as TNF-α, IL-1β, and IL-6 directly induce cardiac hypertrophy and correlated with the severity of hypertrophy." (PMID 33324685, 2020). "TAC was used to establish a mice model of cardiac hypertrophy and cleaved caspase-1 and IL-1β expression levels were detected." (PMID 29440460, 2018). "The results showed that caspase-1 and IL-1β expression levels were significantly up-regulated during cardiac hypertrophy." (PMID 29440460, 2018). "We established cardiac hypertrophy models both in vivo and in vitro to detect the expression of caspase-1 and interleukin-1β (IL-1β)." (PMID 29440460, 2018). "The expression of IL-1β is increased in pressure and volume overload-induced cardiac hypertrophy, and IL-1β induced growth of isolated cardiomyocytes." (PMID 28659798, 2017). "Furthermore, TP53INP1 silencing considerably alleviated D-gal-induced cardiac hypertrophy, myocardial IL-1β and IL-6 levels, and β-gal-positive cells in the KO mice." (PMID 39511427, 2024). "Caspase-1 isinvolved in cardiac hypertrophy by regulating IL-1β and IL-18 expression." (PMID 39484135, 2024). "A mouse model of induced myocardial hypertrophy confirmed a significant increase in the expression of activated caspase-1, IL-1β, and N-GSDMD in the myocardium, demonstrating the importance of pyroptosis in the development of HF based on myocardial hypertrophy." (PMID 38886277, 2024). "However, D-gal-induced cardiac hypertrophy, myocardial IL-1β and IL-6 levels, and β-gal-positive cells were significantly reduced by the overexpression of miR-30a-5p." (PMID 39511427, 2024). "In vitro and in vivo models of cardiac hypertrophy, the expression levels of pyroptosis-related factors were significantly increased, downregulation of Caspase-1 and IL-1β expression by Caspase-1 inhibitors attenuates angiotensin II (Ang II) -induced cardiac hypertrophy." (PMID 35509275, 2022). "Furthermore, TLR4 mediates Ang II-induced cardiac hypertrophy and is associated with myocardial TNF-α and IL-1β levels and NF-κB activity." (PMID 36247184, 2022). "An anti-IL-1β antibody can rescue cardiac hypertrophy after transverse aortic constriction." (PMID 35528518, 2022). "Consequently, downregulation of IL-1β and/or inhibition of its bioactivity in the heart are generally considered to be a certain cardioprotective intervention against cardiac hypertrophy." (PMID 33324685, 2020). "Moreover, Akt activation promotes TNF-α-induced elevation in mRNA levels of IL-6, IL-1α, and IL-1β in cardiac fibroblasts and cardiac hypertrophy in primary cardiomyocytes." (PMID 32831633, 2020). "In addition, plenty of studies evidenced the important role and therapeutic potential of its downstream factor IL-1β in cardiac hypertrophy." (PMID 29440460, 2018).